RN7SKP100 (RN7SK pseudogene 100)
Gene: Miscellaneous RNA gene on chromosome 20 (43,063,326 to 43,063,609, forward strand). Ensembl gene ENSG00000223190.
Homologues: Orthologues: mouse Gm55879 (24% identical). Paralogues in human: 7SK (78% identical), RN7SKP176 (77% identical), RN7SKP255 (77% identical), RN7SKP80 (76% identical), RN7SKP87 (76% identical), RN7SKP9 (76% identical), RN7SKP71 (76% identical), RN7SKP180 (76% identical), RN7SKP250 (76% identical), RN7SKP200 (75% identical), RN7SKP37 (75% identical), RN7SKP78 (75% identical), and 283 more.